LEP (leptin)
Diseases named in the same sentence as LEP in open-access papers (continued):
Sharing a sentence is not in itself a finding about the gene and the disease.
Obesity (continued). "In obesity and related disorders such as T2DM, leptin levels are dramatically reduced; in leptin knowdown animal model, the deletion of the leptin gene and/or its receptor determines constant and continuous hunger, hyperphagia and early onset of severe obesity." (PMID 34652617, 2021). "In contrast, in subjects with obesity, systemic levels of insulin, leptin, and resistin did not increase with gestational age, in line with reduced weight gain in this group." (PMID 34195568, 2021). "Phosphorylation of Tyr985 activates signaling related with SH2-containing protein tyrosine phosphatase 2 (SHP2) and mediates the leptin-stimulated activation of the extracellular signal-related kinase (ERK) pathway, which executes the important functions in thermogenesis and anti-obesity of leptin." (PMID 33849593, 2021). "Obesity leads to a proinflammatory milieu characterized by increased levels of TNF-α, plasminogen activation inhibitor-1, angio-tensinogen, plasminogen activation inhibitor-1, IL-6, leptin, and decreased adiponectin levels which enhance endothelial functions." (PMID 34249177, 2021). "Compared with non-obese controls, patients with NAFLD without obesity had higher fasting glucose levels and a lower adiponectin-to-leptin ratio." (PMID 34853313, 2021). "While circulating leptin is elevated in animal models of ageing in the absence of obesity, it has been reported to decline in elderly adults with severe frailty, but not in community-dwellers." (PMID 33528828, 2021). "This conclusion that leptin resistance at usual weight reflects leptin resistance only in individuals with obesity is not supported by the data since individuals without obesity were not more responsive to leptin." (PMID 34955895, 2021). "The leptin levels were similar between obese and non-obese healthy controls, suggesting that obesity is not a confounding factor." (PMID 34249975, 2021). "It is known that (pre)adipocytes, a predominant cell type present in the adipose tissues, express and secrete a variety of adipokines (leptin, adiponectin, etc.)as well as inflammatory cytokines (TNF-α, IL-1β, IL-6, etc.)and enzymes (iNOS, COX-2, etc.), which confer obesity inflammation." (PMID 34063048, 2021). "In the absence of adequate leptin sensitivity, leptin is unable to exert its ‘anti-obesity’ effects, thereby exacerbating obesity." (PMID 34502119, 2021). "In our study, a 5-week treatment with HF TMS was shown to have a significant effect on the changes in body weight and impulsivity in individuals with obesity, but not on the leptin level changes." (PMID 34173157, 2021). "In 1997, two studies showed that animals with diet-related obesity went through a period in which they did not respond to peripherally administered leptin but still responded to centrally administered leptin directly into the brain." (PMID 34438908, 2021). "Although most obese subjects have high serum leptin levels, increased leptin fails to suppress the progression of obesity." (PMID 34489483, 2021). "In two studies describing LEP wt/-with severe obesity not reporting wt/wt subjects, very low leptin levels in relation to high BMI (4.6 ng/ml, 3.3 ng/ml) or non-detectable leptin were observed." (PMID 34448070, 2021). "Although not previously evaluated for their effects on mitochondrial morphology, the compounds celastrol and withaferin A have been reported to reduce ER stress, sensitize to leptin, and protect from HFD‐induced obesity, outcomes that would be consistent with reduced mitochondrial fission." (PMID 34231322, 2021). "Nonetheless, they do not elucidate the role of leptin genetic background on the concordance of psoriasis and obesity." (PMID 34445769, 2021). "Higher plasma leptin levels have been documented in GDM and may contribute to gestational programming of offspring obesity as leptin is regarded as a permissive signal for puberty initiation." (PMID 33112263, 2021).
Obesity (continued). "We detected genetic correlations between FI and 22 other traits (P < 0.00012, corrected for multiple testing), including obesity-related phenotypes, leptin levels without adjustment for BMI, T2D, high-density lipoprotein cholesterol and triglycerides." (PMID 33402679, 2021). "While based on the energy balance physiology, detailed above, there is a strong rationale for leptin analogues in obesity treatment, metreleptin failed to achieve clinically meaningful weight loss with a mean of just 1.5 kg lost over 24 weeks." (PMID 34680059, 2021). "In our study, the 18:0 Lyso PC treatment group demonstrated regulation of adipokines by inducing a decrease in leptin and MCP-1 and an increase in adiponectin, 18:0 Lyso PC might alleviate a chronic low-inflammation due to obesity." (PMID 34946633, 2021). "Since the majority of obese subjects are leptin resistant, leptin sensitizers, rather than leptin itself, are expected to be anti-obesity drugs." (PMID 34489483, 2021). "Mice lacking leptin (ob/ob mice), display obesity and hypogonadism, which can be restored by leptin treatment." (PMID 34502334, 2021). "When the metabolic markers were correlated with categorical (binary) variables, obesity was associated with lower HDL-C, higher TC/HDL-C ratio, higher leptin, lower adiponectin levels, and higher leptin/adiponectin ratio (p < 0.05) (data not shown)." (PMID 34680168, 2021). "Interestingly, although leptin was identified more than twenty years ago as a key factor in the control of energy balance, studies have shown hyperleptinemia to be correlated with pro-inflammatory conditions in people with obesity, which may lead to the development of atherosclerosis." (PMID 34762789, 2021). "In the occurrence and development of obesity-related OA, SOCS3 may be a key factor in the regulation of TLR4 signaling by leptin." (PMID 34457118, 2021). "The role of leptin in atherosclerosis was confirmed in an experiment on ob/ob mice with the absence of the atherosclerosis-resistant leptin gene, despite obesity and diabetes." (PMID 33735200, 2021). "In this first cross-sectional study, examining breast tissue-specific biomarker expression with combined obesity parameters, we found that mean expression levels of IL-6, TNF-α, and LEP were higher in the breast adipose tissue of women with WC ≥ 86 cm, regardless of BMI." (PMID 34426770, 2021). "Alleviating leptin resistance is an exciting research area as potential anti-obesity therapy as no drugs are known for this function." (PMID 33557185, 2021). "The advanced bone age in the four children and the fact that growth was not impaired in our eight patients suggest that leptin is not necessary for longitudinal growth per se, at least not if obesity is present." (PMID 34002033, 2021). "Indeed, we show that feeding mice a diet supplemented with sodium selenite results in an MR-like phenotype, marked by protection against diet-induced obesity, as well as altered plasma levels of IGF-1, FGF-21, adiponectin, and leptin." (PMID 33783357, 2021). "Overall, leptin is a proinflammatory mediator, activating proinflammatory cells, stimulating the T-helper 1 cell response and production of IL-2, IL-6, and TNF-α, contributing to the systemic inflammatory milieu in obesity." (PMID 33777773, 2021). "The reduction in the leptin-adiponectin ratio with remogliflozin has been reported to improve the metabolic health of adults with overweight or obesity but not diabetes, proposing this as an additional mechanism of body weight reduction with SGLT2 inhibitors." (PMID 34484120, 2021). "It has been well-documented that leptin exerts an inhibitory effect on food intake and increases energy consumption via suppressing the NPY/AgRP neurons and activating α-MSH/CART neurons in the hypothalamus, thus effectively reversing obesity." (PMID 33868169, 2021). "Meanwhile, SOCS3 acting as a negative feedback inhibitor of leptin signaling presented a potential therapeutic prospect for obesity-related OA." (PMID 34457118, 2021).
Obesity (continued). "The high prevalence of both obesity and overweight might be fundamental to the alternating HMW adiponectin and leptin concentrations among respondents in this study." (PMID 34684340, 2021). "In particular, the relationship between Kdm6a and leptin resistance has not been investigated in the obesity." (PMID 34306972, 2021). "Participants with obesity compared to normal-weight participants do not exhibit the expected decrease in leptin and ghrelin secretion following food consumption." (PMID 34404907, 2021). "Furthermore, a specific deletion of Tyr1138 in LepRb or STAT3 in LepRb-expressing neurons leads to hyperphagia and obesity similar to the phenotype observed in db/db mice, suggesting that Tyr1138 in STAT3 is vital for leptin action." (PMID 33849593, 2021). "This study clarified that leptin can regulate Plin5 M6A methylation by promoting FTO to affect the lipid metabolism and energy consumption, providing a theoretical basis for treating diseases related to obesity." (PMID 34638947, 2021). "Our results support the hypothesis that lower levels of fasting leptin in plasma are related to the lower activity of several components of the hypothalamic RAS and halting of the development of obesity in the EVOO group." (PMID 33572630, 2021). "Taken together, these experiments illustrate that leptin does not solely account for obesity-accelerated tumor progression for all cancer types." (PMID 33987528, 2021). "People with obesity can conceivably build-up a condition known as leptin resistance, which implies that their cerebrums no longer react to leptin." (PMID 33946540, 2021). "Summing up, leptin signaling in SF1 neurons plays a key role in energy homeostasis regulation and mediates the proper physiological adaptation to HFD to avoid or delay the onset of obesity." (PMID 34201257, 2021). "The inflammatory hormones leptin, PAI-1, and resistin were all reduced in the HF→LF group compared to both the HF and HF→HFB groups, indicating an improvement in the obese phenotype with the introduction of caloric restriction in established obesity." (PMID 33652785, 2021). "VFT significantly correlated with WC, BMI, hip circumflex (HC), obesity index (OI), fat %, fat mass, insulin, TC, LDL-C, insulin, triglyceride (TG), glucose, homeostatic model assessment for insulin resistance (HOMA-IR) and leptin." (PMID 34746061, 2021). "Although dysfunctional leptin signaling obese models are not the ideal model to study obesity renal disease, SSLepRmutant rats display progressive proteinuria and glomerular injury that is associated with renal hyperfiltration prior to puberty." (PMID 34975523, 2021). "Leptin, TGF-β1, and TLR4 pathway through PREP1 reduction or increased IL-6 expression could be promising new biological markers and therapeutic targets in obesity-related diseases." (PMID 34327205, 2021). "The results showed that high-fat diet (HFD)-related obesity could promote the development of urethane-induced lung cancer in C57BL/6J mice, and the leptin-mediated activation of PI3K/Akt/mTOR/STAT3 pathway was involved in the mechanism." (PMID 33708630, 2021). "Plasma leptin, tumour necrosisfactor-α and non-esterified fatty acid levels are all elevated in obesity andplay a role in insulin resistance and diabetes." (PMID 34987954, 2021). "The current study suggests that LRP2 in the BBB is not involved in leptin transport in vitro or obesity in mice under normal chow diet feeding conditions." (PMID 34066779, 2021). "Leptin induces the expression of TNF-α, IL-6, and IL-1β in adipose tissue cells, contributing to insulin resistance, and is considered one of the links between obesity, insulin resistance, and atherosclerosis." (PMID 33520042, 2021). "ASrAogen transgenic rats, with decreased glial expression of angiotensinogen, do not develop hypertension and obesity during aging, but its plasma levels of leptin are lower than in normal rats." (PMID 33572630, 2021).
Obesity (continued). "In essence, the concept of BMI fails to capture an accurate obesity representation by underestimated its prevalence, particularly in women with elevated leptin levels (>30 ng/mL)." (PMID 34574696, 2021). "Our findings also suggest that the effect of leptin on IL-17A production in CD4+ T cells is not influenced by obesity status." (PMID 35111163, 2021). "Thus, this study aims to compare leptin, ghrelin, adiponectin and IGF-1 levels of pre-feed and post-feed breast milk in mothers with obesity and normal weight." (PMID 34348809, 2021). "Understanding the molecular interplay between insulin, leptin, IGF-1 and inflammation may be crucial in understanding the relation of IVD degeneration and obesity." (PMID 33396484, 2020). "The differences in these results are attributed to the fact that pathologic mechanisms of ObD mice, which are accompanied by leptin and insulin resistance, are not solely identical to those of the high fat-induced obesity model." (PMID 32842462, 2020). "The good control of obesity under ALA treatment could also be derived from low abdominal fat and an increase in adiponectin/leptin ratio." (PMID 33142857, 2020). "Similar to obesity, adiponectin has a negative correlation to BMI in HF whilst leptin and insulin correlated positively with BMI." (PMID 33117276, 2020). "Humans and mice lacking leptin have hyperphagic obesity, hyperinsulinemia, and decreased energy expenditure demonstrating the prominent role that leptin plays in energy homeostasis." (PMID 33382813, 2020). "A triple-masked, randomized, placebo-controlled trial conducted by Kelishadi and colleagues found a significant decrease in Apo B/ApoA-I ratio, ox-LDL, leptin and malondialdehyde, total and LDL-cholesterol and hs-CRP in children with obesity, after they had received zinc sulfate supplementation." (PMID 32947869, 2020). "Although obesity is considered a low-grade systemic inflammatory state, in the present study, we did not observe differences in us-CRP and in most of the cytokines analysed in blood serum (IL-6, TNF-α, IL-1β, IL-10, MCP-1 and leptin)." (PMID 33489104, 2020). "Although plasma adiponectin levels did not change after the weight gain, elevated leptin levels were noted in mice with high-fat diet-induced obesity." (PMID 32104148, 2020). "Nevertheless, the mechanisms binding leptin to the HPG axis and obesity are still not fully understood and the research results on the role of leptin in infertility development remains unclear." (PMID 32397485, 2020). "Previous studies have also shown that hormones and the nutritional status influence serum leptin levels, independent of obesity." (PMID 32655492, 2020). "For example, leptin and insulin interact with hypothalamic neuropeptides NPY, MCH, and α-MSH, not only regulating appetite, but also activating the SNS, possibly contributing to obesity-related hypertension." (PMID 33644105, 2020). "As opposed to leptin, APN levels are inversely associated with obesity, myocardial infarction, and hypertension." (PMID 32566092, 2020). "Since nesfatin-1 ́s actions are preserved in conditions of leptin resistance, the present findings render the NUCB2/nesfatin-1 system an appealing target for the development of novel therapeutical treatments towards obesity." (PMID 32353862, 2020). "However, the PNS-induced alterations in the gut microbiota could not reverse obesity in leptin-deficient mice, which showed that defective leptin signaling is considered responsible for the negative effects of the PNS-mediated modulation of the gut microbiota on adiposity." (PMID 33042284, 2020). "Both endogenous high leptin levels and treatment with exogenous leptin are not effective in treating obesity due to leptin resistance." (PMID 32375231, 2020). "Indeed, in obesity, there is an increase in FFA and leptin release by WAT adipocytes that can act in an autocrine manner to further cause adipocyte dysfunction." (PMID 33207733, 2020).
Obesity (continued). "In both the DIO and ob/ob mouse models of obesity, which have high and nonexistent circulating levels of leptin respectively, total plasma and hepatic ceramide levels are increased." (PMID 33133017, 2020). "Although obesity is characterized by a diminished anorectic response to exogenous leptin in the central nervous system, DIO mice still exhibit leptin actions, and leptin can even increase thermogenesis in interscapular BAT via a hypothalamus-independent pathway." (PMID 33042284, 2020). "Even though low leptin levels are not observed in human NAFLD, leptin-deficient mice (ob/ob) exhibit obesity, hyperlipidemia, insulin resistance, and steatosis but without fibrosis." (PMID 32872474, 2020). "When we compared the obese and nonobese women, we found that obesity status had an interaction effect on leptin level." (PMID 31914480, 2020). "As opposed to leptin, serum adiponectin levels in adults are inversely related to the amount of body fat, with adult patients with obesity having decreased circulating adiponectin levels." (PMID 33137934, 2020). "Obesity may induce cardiovascular disease via increased serum levels of low-density lipoprotein cholesterol (LDL cholesterol), total cholesterol (TC), serum leptin, and triglyceride (TG)." (PMID 32668680, 2020). "Its possible regulation by insulin and leptin, two hormones closely involved in the regulation of obesity and insulin resistance, has not been systemically explored." (PMID 31936857, 2020). "MSG obesity is an early-onset obesity resulting from MSG-induced lesions in arcuate nucleus to neonatal mice, further disrupting the hypothalamic signaling cascade of leptin action." (PMID 32477009, 2020). "Interestingly, rats with diet-induced obesity exhibit increased TRH and an upregulation of the HPT axis, despite leptin resistance in the main site of action of leptin, the ArcN." (PMID 32538782, 2020). "In this study, we performed a systematic review and meta-analysis on a wide range of obesity related factors including values of BMI, WC, Weight, leptin, and adiponectin that have not been reported before." (PMID 33335235, 2020). "Taken together, these observations indicate that obesity, OSA and hyperleptinemia/leptin resistance are conditions that frequently co-exist in the same individual, suggesting that they could share a similar pathophysiology." (PMID 32698380, 2020). "Additionally, we collected parameters associated with metabolic health in obesity (waist-hip ratio, waist-height ratio, leptin levels, body fat percentage, fat mass index, insulin resistance) to investigate recently proposed mechanistic explanatory models of why olfaction may be altered in obesity." (PMID 33328935, 2020). "From this point of view, the anti-obesity mechanism of ASX might be mediated by improving adipokine levels (i.e., reducing leptin levels and increasing adiponectin levels)." (PMID 32260306, 2020). "SST and leptin exert opposing effect on appetite in contrast to reciprocal roles between leptin and BDNF in hypothalamus, indicating indirect relation between SST and BDNF in regulation of eating behaviour and obesity." (PMID 32272767, 2020). "Interestingly, the overexpression of leptin and some adipocytokines in the offspring of the HFD group stimulates the secretion of inflammatory factors, such as monocytes and macrophages, which in turn might be another mechanism of obesity and increased risk of insulin resistance." (PMID 32596284, 2020). "The levels of leptin, GIP, and neuropeptide showed sex-dimorphism in obesity." (PMID 33644105, 2020). "When fed with a HFD, these mice gain similar weight to their wild-type (WT) littermate controls; however, they are less prone to develop liver steatosis, dyslipidemia, and leptin resistance, making hepatic CB1R a central regulator of obesity-related liver complications." (PMID 33210603, 2020).